TPM1 (tropomyosin 1)
Diseases named in the same sentence as TPM1 in open-access papers (continued):
Sharing a sentence is not in itself a finding about the gene and the disease.
infection (3 papers, 2015 to 2025). The state of being infected such as from the introduction of a foreign agent such as serum, vaccine, antigenic substance or organism. "Interestingly, significantly elevated expression of six above-mentioned associated genes (Pmepa1, Mamstr, Rasip1, Tpm1, Itih4 and Ogdhl) in mice total liver tissues was also observed from the seventh week (S. japonicum spawn in large numbers) after infection." (PMID 35493725, 2022). "To identify which TPM1 variants were repressed in the context of KSHV infection, we infected HUVECs with KSHV and harvested the cells at 3 and 7 days post-infection (dpi)." (PMID 26263384, 2015). "Consequently, by targeting both HMW-TPM1 isoforms expressed in HUVECs like miR-K2 and KSHV de novo infection, si-Exon12 is a valuable tool to mimic the effect of miR-K2 and KSHV infection on TPM1 isoforms in endothelial cells." (PMID 26263384, 2015).
neurodegenerative disease (3 papers, 2022 to 2025). A disorder of the central nervous system characterized by gradual and progressive loss of neural tissue and neurologic function. "More recently, we have reported TPM1 elevation in aged retinas and in the retinas of AD mouse models, indicating the potential pathological role of overexpressed TPM1 in neurodegenerative diseases." (PMID 36241997, 2022). "To explore whether TPM1 had a potential role in age‐related neurodegenerative diseases, we examined TPM1 expression in young 5xFAD and TgCRND8 mice, two well‐known rodent AD models." (PMID 35148456, 2022).
neurological disease (2 papers, 2017 to 2024). "Tropomyosins (TPM) are a family of actin-related proteins associated with the pathology of neurodegenerative and neurological diseases, and TPM1 is a widely expressed actin-binding protein in the TPM family." (PMID 38790269, 2024).
bone disorder (1 paper, 2024). "Remarkably, we also observed that SO-EVs exhibit reduced levels of TPM1 compared to YO-EVs, raising the possibility that EV-mediated signaling from osteocytes may contribute to age-related bone disorders." (PMID 38664789, 2024).
brain diseases (1 paper, 2022). "Our findings suggest that TPM1 could be a potential target for therapeutic intervention in brain diseases." (PMID 36241997, 2022). "Collectively, our results demonstrate that TPM1 is an important regulator of pro-inflammatory gene expression in microglia and that TPM1 could be a potential target for therapeutic intervention in brain diseases." (PMID 36241997, 2022).
mitochondrial disease (1 paper, 2023). "Defects in sarcomere genes, such as MYH7, MYBPC3, TNNT2, TPM1, ACTC1, and TTN have been reported as causative for LVNC and LVNC is also commonly associated with mitochondrial diseases." (PMID 37186429, 2023).
vascular disorder (1 paper, 2021). A general term used to describe any disease affecting blood vessels]. "Therefore, products of the TPM1 gene may be a potential therapeutic target for the treatment of proinflammatory vascular disorders." (PMID 34604206, 2021).
TPM1 also shares sentences with these, for which no sentence is quoted: familial hypertrophic cardiomyopathy (5 papers); esophageal cancer (3); arteriosclerosis obliterans (2); B-cell lymphoma (2); fibrosis (2); Hypertension (2); Parkinson disease (2); acute lymphoblastic leukemia (1); alopecia (1); aortic stenosis (1); arrhythmogenic right ventricular cardiomyopathy (1); arthrogryposis (1); asymmetrical septal hypertrophy (1); atrial fibrillation (1); Barrett esophagus (1); Behçet's disease (1); bladder urothelial carcinoma (1); Blepharocheilodontic syndrome 2 (1); Branchio-oculo-facial syndrome (1); congenital myopathy (1); Coronary Heart Disease (1); Danon disease (1); dementia (1); diabetic nephropathy (1); Fabry disease (1); familial dilated cardiomyopathy (1); familial hypertrophic cardiomyopathy 3 (1); fibrosarcoma (1); genetic disorder (1); glioblastoma (1).
A further 39 diseases each share a sentence with TPM1 in 1 paper.